RUNX1 (RUNX family transcription factor 1)
Diseases named in the same sentence as RUNX1 in open-access papers (continued):
Sharing a sentence is not in itself a finding about the gene and the disease.
leukemia (continued). "RUNX1 and RUNX2 expression was found to be quite high in head and neck cancer, kidney cancer, leukemia, and pancreatic cancer, according to our findings." (PMID 35522574, 2022). "Monitoring RUNX1-FPD patients by sequencing panels to detect clonal hematopoiesis and/or alterations by variant allele fractions of already known variants may offer the opportunity to intervene at the pre-leukemic stage, prior to the appearance of overt MDS or frank leukemia." (PMID 35884491, 2022). "It is interesting that both the patients with LMNB1::PPP2R2B fusion carried ETV6::RUNX1 fusion, implying that LMNB1::PPP2R2B fusion played a role in the pathogenesis of ETV6::RUNX1-positive leukemia." (PMID 36612032, 2022). "The identified variants have been reported in AML, displaying variable effects on RUNX1 protein functions, including CBFB dimerization and DNA binding, in addition to leukemia transformation." (PMID 32782381, 2021). "Using drug sensitivity profiling of primary leukemia cells and CRISPR/Cas9 RUNX1 gene-edited CML cell lines, we identified novel effective targeted therapies and CD19-CAR T cells as a promising immunotherapeutic option." (PMID 32782381, 2021). "Our findings unveil the role of CBFA2T3 also as a transcriptional activator for RUNX1 in human PreB lymphoblasts, and demonstrate the existence of a new RUNX1 and CBFA2T3 driver-loop in ETV6-RUNX1 BCP-ALL leukemia." (PMID 33743795, 2021). "Kataegis occurred particularly frequently at a per-sample level between chr20:31050000-31080000 which corresponds to the region of NOL4L/C20orf112 (chr20:31,030,862-31,071,385) a known fusion partner of RUNX1 and PAX5 in leukaemia." (PMID 33632293, 2021). "Approximately one from ten thousand RUNX1/RUNX1T1, PML-RARα, or KMT2A-MLLT3 positive newborns will finally suffer from overt leukemia, according to these estimations." (PMID 33803739, 2021). "SUMO1 modification of PKM2 recruits and promotes degradation of RUNX1 via a SUMO-interacting motif, resulting in blockage of myeloid differentiation of NB4 and U937 leukemia cells." (PMID 33473116, 2021). "This is particularly important for leukemia with MLL-rearrangements, where RUNX1 can interact with MLL and NFκB." (PMID 34594227, 2021). "Although there is evidence that some leukemic translocations, such as ETV6/RUNX1, occur at substantially higher rates in utero than the rate of overt leukemia, there may be translocations whose frequency of in utero initiation is near that of the specific leukemia subtype to which they give rise." (PMID 33968846, 2021). "This study overexpressed and knocked down RUNX1 expression in THP-1 human leukemia cells and CD34+ hematopoietic stem/progenitor cells to investigate the biological functions affected by dysregulated RUNX1." (PMID 34434964, 2021). "For example, RUNX1 is active in both leukemias and FBM, but past work has also shown that RUNX1 expression is higher in KMT2A-AFF1 ALLs than in KMT2A-MLLT3 AML." (PMID 34088716, 2021). "The first is that the relative frequency of childhood ALL, and ETV6/RUNX1 ALL in particular, compared with childhood AML has led to more investigation of this leukemia subtype." (PMID 33968846, 2021). "The molecular basis includes the prevalent SUMO1 modification across leukemia cells which breaks up tetrameric PKM2 to dimeric form, and downregulates RUNX1 through direct interaction." (PMID 33473116, 2021). "Other key leukemia-specific hits include MYB, MED13L, HOXA10, and the binding partner of RUNX1, CBFB." (PMID 34088716, 2021). "Both human MLF1 and Drosophila mlf were shown to be necessary for the expression of RUNX1-ETO in a stable manner in human and Drosophila leukemia cells, respectively." (PMID 32708107, 2020). "Expression of RUNX1‐ETO9a led to rapid induction of leukaemia in mice and co‐expression of RUNX1‐ETO and RUNX1‐ETO9a resulted in an earlier onset of AML with a block in myeloid differentiation at a more immature stage." (PMID 34766123, 2020).
leukemia (continued). "This recurring chromosomal translocation results in generation of the aberrant oncofusion protein, RUNX1-ETO, which is an established driver of leukemia development." (PMID 32029705, 2020). "Recently, we demonstrated that HSCs require a functional RUNX1 to maintain adequate PU.1 levels, which is critical for RUNX1-ETO leukemia development in mouse transplantation models." (PMID 30654457, 2019). "To evaluate if Id1 overexpression correlates with the development of leukemia in mice, we examined Id1 expression in the spleen, liver, and BM of mice induced by ASXL1-R693X, RUNX1-R135T, and combination of ASXL1 and RUNX1 mutants as well as control." (PMID 31640815, 2019). "Using in vitro and in vivo screens to identify essential RUNX1/ETO transcriptional targets in AML, Martinez-Soria identify CCND2 as required for leukemia maintenance and self-renewal." (PMID 30300583, 2018). "In leukemia, ERG targets transcription factors such as GATA2, which is an important regulator of hematopoietic stem cell and megakaryocyte development and, RUNX1, which is involved in the development of normal hematopoiesis." (PMID 30303964, 2018). "As immune disease-related genes, MYD88 (81.4%) and BCL10 (25.9%) in NF-ĸB signaling, CD79B (59.2%), PAX5 (22.2%), and BCR (7.4%) in B-cell development, and MYH11 (25.9%), RUNX1 (7.4%), and TET2 (7.4%) in leukemia were observed." (PMID 29937999, 2018). "JUN (c-JUN) is induced upon RUNX1/ETO expression, and it scored in the in vivo RNAi screen as being essential for leukemia propagation." (PMID 30300583, 2018). "The epigenetic abnormalities result in the upregulation in leukaemia blasts of an array of genes which are normally expressed in haematopoietic stem cells, such as HOXA9, MEIS1, HMGA2 and RUNX1." (PMID 28819864, 2018). "This study also identified immune disease-related genes associated with somatic mutations such as MYD88 and BCL10 in NF-κB signaling, CD79B, PAX5, and BCR in B-cell development, and MYH11, RUNX1, and TET2 in leukemia." (PMID 29937999, 2018). "Accordingly, reduction of Runx1 or Runx2 expression inhibited CBFβ–SMMHC-mediated differentiation block in embryos and leukemia onset in mice." (PMID 29755956, 2018). "In mice, WT1 cooperates with the RUNX1/RUNX1T1 (AML1/ETO) fusion gene in the induction of acute leukemia, further emphasizing a role for WT1 in leukemia development." (PMID 29152069, 2017). "Clonal haematopoiesis in asymptomatic RUNX1 carriers under the age of 50 years was already reported 9 suggesting together with our results that the identification of clonal haematopoiesis before leukaemia development in FPD/AML patients could serve as a marker of pre‐leukaemic state." (PMID 27997762, 2017). "Pediatric ETV6/RUNX1-positive leukemia generally has favorable long-term remission and survival rates, but as in ALL initial manifestation, ETV6/RUNX1 is the most common structural genetic aberration in childhood B-cell precursor (BCP) ALL at first relapse." (PMID 28418909, 2017). "Here, we provide a comprehensive overview of lncRNA expression in ETV6/RUNX1-positive BCP-ALL and analyze the transcriptional consequences of lncRNA modulation in the context of ETV6/RUNX1 rearranged leukemia." (PMID 27650541, 2016). "Thus, placing the ETV6/RUNX1 transgene under control of the Cd19 promoter may be too late to allow for B cell progenitor leukemia development when combined with BCL2 overexpression, but still allowing to promote autoimmune mature B cell abnormalities that aggravate glomerulonephritis." (PMID 26919255, 2016).
leukemia (continued). "MiR221/222 and miR223 are directly repressed by RUNX1/ETO, which provides a good example of the intricate relationship between RUNX1, RUNX1/ETO and microRNAs in normal differentiation and leukemia." (PMID 26990877, 2016). "Here, we conducted a comprehensive analysis of the long non-coding RNA transcriptome in ETV6/RUNX1-positive BCP-ALL, one of the most frequent subtypes of pediatric leukemia." (PMID 27650541, 2016). "The RUNX1 (AML1) and CBFB genes are among the most commonly involved in human leukemias where they are affected by chromosomal translocations that frequently generate fusion oncoproteins." (PMID 27056890, 2016). "We also noted strong inverse correlations between RUNX1 and RAG1/RAG2 mRNA expression in a panel of human leukemias and lymphomas." (PMID 27056890, 2016). "The HATs, such as p300, CBP, MOZ and MORF, interact with Runx1 (or AML1), which is one of the most frequent targets of chromosomal translocations in leukemia." (PMID 26784169, 2016). "However, although a possible link between a genetic predisposition factor in the pathogenesis of autoimmunity and leukemogenesis has been recently proposed, we are not aware of any case reports for ETV6/RUNX1+ leukemia patients associated with autoimmune disease (and/or glomerulonephritis)." (PMID 26919255, 2016). "However, this residual RUNX1 activity may be enough to drive leukemia development." (PMID 27542261, 2016). "A previous study by Fernando and colleagues also evaluated lncRNA expression signatures in genetic subtypes of human BCP-ALL using 14 ETV6/RUNX1, 15 TCF3/PBX1 and 15 MLL-rearranged leukemia specimens." (PMID 27650541, 2016). "For instance, JMJD1C functions as a co-activator for Runx1-Runx1T1 in acute myeloid leukemia cell lines and for HoxA9 in mixed lineage leukemia-AF9 and HoxA9-driven leukemia." (PMID 27649575, 2016). "All together, our study defined a unique lncRNA expression signature associated with ETV6/RUNX1-positive BCP-ALL and identified lnc-RTN4R-1 and lnc-NKX2-3-1 as lncRNAs that might be functionally implicated in the biology of this prevalent subtype of human leukemia." (PMID 27650541, 2016). "The RUNX1 transcription factor and its oncogenic derivative RUNX1–ETO are paradigms of transcriptional and epigenetic reprograming in leukemia." (PMID 26483790, 2015). "Thus genes such as RUNX1 (which may contribute to childhood leukaemia in people with DS), APP (a key Alzheimer disease gene) and SYNJ1, RCAN1 and ITSN1, which have been linked to endosomal/synaptic abnormalities are unlikely to contribute to the phenotype of this mouse model of DS." (PMID 23596509, 2013). "RUNX1 and CBFB are frequent targets of chromosomal abnormalities in hematopoietic malignancies, particularly in leukemia (also referred to as CBF leukemia or CBFL)." (PMID 23344057, 2013). "Similar to RUNX1, the strongest evidence for a pro-oncogenic function for RUNX2 comes from studies in lymphoma/leukemia models; however RUNX2 was also shown to play a role in invasive bone, breast, prostate, thyroid and pancreatic cancer." (PMID 24124450, 2013). "For some of the genes involved, including MLL, PML, RARA and AML1 (RUNX1) a relatively large number of translocation breakpoints from de novo and therapy related leukemia cases have been determined at the base pair level." (PMID 22829791, 2012). "This included two leukemia cell lines, RCH-ACV and REH, known to carry the TCF3:PBX1 and ETV6:RUNX1 fusion genes, respectively, and four prostate cancer samples positive for the TMPRSS2:ERG fusion gene." (PMID 19152679, 2009). "Similar studies of umbilical cord blood samples have shown that the frequencies of ETV6/RUNX1 and RUNX1/ETO, for example, are 100 times higher in neonates than in pediatric leukemia patients." (PMID 21637673, 2009).
leukemia (continued). "Using this array, proof of principle was demonstrated by detection of known fusion genes (such as TCF3:PBX1, ETV6:RUNX1, and TMPRSS2:ERG) from all six positive controls consisting of leukemia cell lines and prostate cancer biopsies." (PMID 19152679, 2009). "Our findings lead us to propose the following mechanism: PTBP1, which does not have a DNA binding domain, binds RUNX1 and is recruited to the promoter regions to drive expression of genes essential for leukemia cell survival." (PMID 41214140, 2026). "To address whether RUNX1 binds PTBP1 in these cells, we compared the expression of PTBP1 in leukemia cells and HSPCs." (PMID 41214140, 2026). "Most frequently, ETV6::RUNX1+ B-ALL harbors deletions of the second, non-translocated ETV6 allele, implying that the initial gene fusion predisposes individuals to leukemia, while subsequent ETV6 deletion acts as a promoting factor." (PMID 40243620, 2025). "Our findings suggest that the physical interaction between RUNX1 and the JMJD1C N-terminus may explain the functional importance of JMJD1C in leukemia." (PMID 39450904, 2025). "The absence of leukemia in Runx1+/R188QMx1-CreCbfb+/56M mice strongly suggests that the leukemia-initiating activity is broadly impaired across all hematopoietic populations, including the AMP population." (PMID 40763310, 2025). "The RUNX1 requirement for leukemias with CBFβ and MLL translocations further supports the idea that RUNX1 may actually promote the growth of many types of leukemia cells." (PMID 39450904, 2025). "JMJD1C or the JMJD1C/RUNX1 interaction are such candidates for targeted therapies as JMJD1C is required for the survival of various leukemias but not for HSC homeostasis." (PMID 39450904, 2025). "Conversely, downregulated genes in immature bone marrow progenitors upon knockout of CBFA2T3 were enriched in bone marrow cells from Runx1+/R188QMx1-CreCbfb+/56M mice that did not develop leukemia." (PMID 40763310, 2025). "To rule out the possibility that the reason Runx1+/R188QMx1-CreCbfb+/56M mice did not develop leukemia was because of RUNX1 haploinsufficiency, we examined Runx1+/fMx1-CreCbfb+/56M mice, in which one Runx1 allele can be deleted by Cre." (PMID 40763310, 2025). "Notably, these pathways were also enriched in the DEGs identified in the AMP population between Mx1-CreCbfb+/56M and Runx1+/R188QMx1-CreCbfb+/56M mice, further emphasizing their critical role in Cbfb-MYH11–induced leukemia." (PMID 40763310, 2025). "However, ETV6::RUNX1, TCF3::PBX1, and T‐ALL had low MTXPG intracellular accumulation in leukemia cells." (PMID 39485718, 2024). "Experiments with transgenic mice have shown that RUNX1- RUNX1T1 knock-in led to the expansion of myeloid progenitor cells but did not block their differentiation nor initiate leukemia." (PMID 39272967, 2024). "RUNX1 transcription is regulated by a distal promoter that is directly inhibited by PITX1 through their interaction, thus suppressing T cell development and promoting leukemia." (PMID 37841446, 2023). "The regulatory networks governing the top deregulated genes in adult and pediatric RUNX1/RUNX1T1 AML patients include several transcription factors, intermediate proteins and kinases, which orchestrate the establishment and maintenance of leukemia." (PMID 36980682, 2023). "The expression of the RUNX1/RUNX1T1 fusion protein alone is not sufficient to induce leukemia, but it is a complex process which includes the deregulation of various pathways." (PMID 36980682, 2023). "Previous studies have shown that RUNX1 transcription factors associate with co-activators CBP and p300, whereas leukemia-associated RUNX1-ETO proteins do not interact with CBP/p300 family proteins, but rather with co-repressive proteins including HDACs." (PMID 37760803, 2023).
leukemia (continued). "In this pursuit, we focussed on human AML driven by MLL-rearrangements, RUNX1-ETO translocations and those characterized by complex karyotypic lesions and assessed if and how those different leukaemia contexts would display a characteristic phenotypic modulation in response to MYB suppression." (PMID 37996430, 2023). "ETV6::RUNX1 is known to be a weak oncogene unable to induce leukemia in the absence of secondary genetic alterations." (PMID 37670323, 2023). "When injected into immunocompromised NOD/SCID mice the RUNX1::RUNX1T1 transduced cells were able to engraft but did not elicit leukemia." (PMID 38201282, 2023). "MDS patients with mutated RUNX1 had inferior leukaemia‐free survival (LFS) and overall survival (OS) than those without RUNX1 mutations." (PMID 36467848, 2022). "Although we focused our analysis on RUNX1, whose role in KMT2A-FP leukemias has been observed previously, placing RUNX1 in the context of the KMT2A-AFF1 GRN allows us to capture complex aspects of the KMT2A-AFF1:RUNX1 regulatory axis." (PMID 34088716, 2021). "Because RUNX1 shRNA-treated THP-1 cells also showed impaired differentiation potentials, we questioned whether CENPE could further rescue leukemia cell differentiation ability." (PMID 34434964, 2021). "This depleted cell number phenotype in the RUNX1 KD THP-1 cell was similar to that observed in mouse MLL-AF9 and MLL-AF4 cells when treated with RUNX1 shRNA, This similarity indicated that the function of dysregulated RUNX1 in MLL fusion leukemia was likely conserved." (PMID 34434964, 2021). "Western blot further confirmed increased the expression of RUNX1 in leukemia cells lacking PKM2 expression." (PMID 33473116, 2021). "Among these were RUNX1, MYB, and TAL1, 3 out of 8 DE genes (Fisher Exact test, odds ratio = 93, p = 2 × 10−5) that have previously been identified as part of a core transcriptional circuitry important to our leukemia model system." (PMID 33526072, 2021). "This role of RUNX1 is not as prevalent in leukemia as the literature suggests that RUNX1 mainly promotes leukemic cell growth." (PMID 34434964, 2021). "Consequently, RUNX1/RUNX1T1 reprograms a massive transcriptional network to establish and maintain leukemia." (PMID 33217477, 2021). "Although a number of attempts have been made to generate its mouse model, RUNX1-ETO induction alone did not induce leukemia in most cases." (PMID 34148054, 2021). "Our study sheds light on the earliest events occurring after RUNX1-ETO expression in a human primary cell setting and demonstrates a dissociation between block in differentiation and cell proliferation, considered the two hallmarks of leukemia." (PMID 32460028, 2020). "Additionally, the ETV6/RUNX1 fusion gene can be stabilized at the mRNA level by the RNA-binding protein IGF2BP1, which is overexpressed in this type of leukemia." (PMID 32102485, 2020). "RUNX1‐ETO expressing CD34+ cord blood cells maintain self‐renewal and multipotent differentiation, but when transplanted do not cause leukaemia in NOD/SCID mice, consistent with the transgenic mouse models." (PMID 34766123, 2020). "Here, the authors perform proteogenomic and Hi-C analyses of this leukemia and the ETV6/RUNX1 subtype and show that CTCF and cohesin expression are low in hyperdiploid cases and transcriptional dysregulation in relation to topologically associating domain borders in some of these cases." (PMID 30944321, 2019). "The model described here can act as a useful tool in this endeavour and could be relevant to study other common leukaemia-initiating events, such as ETV6/RUNX1 and MLL fusion events." (PMID 30867444, 2019). "A specific leukemia where cut-and-run could play a significant role is ALL where patients bear the ETV6/RUNX1 (TEL/AML1) translocation." (PMID 30905508, 2019).